CSF2 (colony stimulating factor 2)
Diseases named in the same sentence as CSF2 in open-access papers (continued):
Sharing a sentence is not in itself a finding about the gene and the disease.
infection (continued). "In the early stage of inflammation, monocytes recruited to the site of inflammation are more likely to develop into proinflammatory macrophages (M1) than M2, which is orchestrated by GM-CSF (CSF2), in order to fight ongoing infection." (PMID 32900001, 2020). "Of these genes, SAA2 was the most significant (-10logp-value of 81); the distinctive genes in the SARS-CoV-2’s infection response were CSF3, CSF2, IL1B, and PTGS2." (PMID 33301474, 2020). "Gene expression analysis revealed a subset of genes, including Csf2, Cxcl1, Fas, and Cxcl2, were upregulated during T3DPL infection independently of RIG-I and/or IFN activities." (PMID 32956403, 2020). "The DEGs involved in cytokine signaling were also up-regulated following infection with EV-F7, and included IL-6, IL-11, leukemia inhibitory factor (LIF), granulocyte-macrophage colony-stimulating (GM-CSF), and colony stimulating factor 2 (CSF2)." (PMID 30545363, 2018). "CSF2 and CCL20 were significantly higher in cPLA2α−/− than cPLA2α+/+mice at 12 and 24 h after infection." (PMID 27501951, 2016). "The expression of genes encoding other cytokines were also significantly increased during infection, including the pro-inflammatory cytokines IL1, IL8, tumor necrosis factor alfa (TNF-α), interferon gamma (IFN-γ), and CSF2." (PMID 27982111, 2016). "Analysis of differentially expressed genes in the LC group compared with the CC group at day 90–180 after infection identified an increase of multiple proinflammatory markers, such as IL6, NLRP3, TNF, JAK2, CSF2, IL1B and IL10, in the LC compared with the CC group." (PMID 41388153, 2026). "However, at 14 days post-infection, the percentage area stained for MPO was significantly higher in WT mice compared to Csf2 KO mice." (PMID 41190069, 2025). "Indeed, Csf2-/-/μMT mice had a reduced number of CD4+ T cells in tracheobronchial lymph node as well as in lungs and BAL 4 days post-infection." (PMID 35493510, 2022). "CSF2-cFLiMo–derived alveolar macrophages are superior to CSF1-cBMM–derived alveolar macrophages in reconstitution of empty alveolar macrophage niches and prevention of morbidity to infection with influenza virus." (PMID 35393945, 2022). "PrimePCR array analysis of hNS/PCs showed that the mRNA levels of inflammatory cytokine related genes (IL-1A, TNFα, IL28A, IL29, NF-KB2), chemokines (CSF2, CCL3, CCL4, CXCR3),TLRs (TLR3, TLR8), IL-10, and Casp9 were all reduced in the Smaducin-6 treated group following ZIKV-FSS13025 infection." (PMID 32544190, 2020). "STAT5 induced expression of CSF2 results in increased production of monocytic chemoattractant protein 1 (CCL2) by monocytic cells, which functions in the recruitment of monocytic cells, including macrophages to the sites of injury or infection." (PMID 24339989, 2013). "At individual gene expression level several transporter genes (Cacna1i, Slc4a1, Slc15a1) and immune response genes (Igsf4d, Ilf1, Csf2) showed no overlap possibly due to infection kinetics." (PMID 17850650, 2007). "The infection of MDMs with Mtb opsonized with hSAA-1, compared to the infection with nonopsonized bacilli, led to at least a 2-fold increase in the concentrations of CSF2, CSF3, IL-1α, IL-1β, IL-6, IL-12, CCL15, and TNF-α with the most potent 10-fold increase observed for CCL5." (PMID 37781389, 2023). "Of the 14 Th1 response genes tested, the expression levels of 8 genes (IL2, IFNG, CSF2, TLR4, CD4, IRF1, SOCS5 and STAT4) were significantly elevated at 2 weeks and several of these (IL2, IFNG, TLR4, CD4 and STAT4) had similar expression levels at 4 and 8 weeks post-infection." (PMID 23448601, 2013). "CSF2 and CCL2 protein levels were higher in CF cells than in CTRL cells and increased further with time after infection, although the differences were not statistically significant." (PMID 26485688, 2015).
infection (continued). "It would be interesting to evaluate in those murine models of Gram-negative pathogens infections whether the CRL1505 or CRL1506 strains can also modulate the levels of CSF3, IL-1β, IL-12, CSF2, CCL2, CCL8, and adhesion molecules as we observed in this work." (PMID 40141330, 2025). "In addition, DMI enhances the Csf2 mRNA level in the lung tissues from mice infected with Mtb and BCG, whereas it enhances Ifng mRNA expression in the lungs during BCG, but not Mtb, infection." (PMID 36882813, 2023). "Additionally, our findings regarding IFN-α, IL1β, IL8 and CSF2 are consistent with a previous gene expression study that demonstrated no significant upregulation of these innate markers in animals infected with PRRSV, regardless of whether the infection is persistent or non-persistent." (PMID 37409113, 2023).
respiratory disease (6 papers, 2019 to 2022). "Colony stimulating factor 2 (CSF2) is a cytokine-coding gene associated with respiratory diseases such as pulmonary alveolar proteinosis." (PMID 34376762, 2021). "The analysis yielded seven SARS-CoV-2 specific genes including CSF2 [GM-CSF] (colony-stimulating factor 2) and calcium-binding proteins (such as S100A8 and S100A9), which are known to be involved in respiratory diseases." (PMID 34376762, 2021).
kidney disease (3 papers, 2015 to 2024). "Secretion of TNF, CSF2, MMP9, CTGF and PAI-1 were measured, as these molecules are known to modulate kidney disease progression in various animal models of CKD." (PMID 39005931, 2024). "The role of CSF2 in kidney disease has not been well investigated to date." (PMID 39240898, 2024).
CSF2 also shares sentences with these, for which no sentence is quoted: autoimmune PAP (79 papers); neuroblastoma (75); metastatic melanoma (50); experimental autoimmune encephalomyelitis (45); hepatocellular carcinoma (45); bacterial infection (43); inflammation (39); cryptococcosis (31); dengue (26); acute respiratory distress syndrome (23); allergic asthma (23); Immunodeficiency (23); lymphoma (21); non-small cell lung carcinoma (21); pancreatic ductal adenocarcinoma (21); leukocytosis (20); osteoarthritis (20); Cognitive impairment (18); osteosarcoma (18); infectious disease (17); lupus (17); metastatic disease (17); pancreatic adenocarcinoma (17); co-infection (16); Cryptococcal meningitis (16); lymphopenia (16); triple-negative breast carcinoma (16); hematological malignancies (15); HIV-1 infection (15); leukopenia (15).
A further 581 diseases each share a sentence with CSF2 in 14 papers or fewer.